DNMT1 (DNA methyltransferase 1)
Diseases named in the same sentence as DNMT1 in open-access papers (continued):
Sharing a sentence is not in itself a finding about the gene and the disease.
ovarian carcinoma (continued). "DNMT1 gene deletion confers resistance to DNMTi, with reduced levels of DNA damage and apoptotic/cytotoxic effects in colorectal, breast, and ovarian cancer cells." (PMID 39057134, 2024). "DNMT1 gene deletion confers resistance to DNA methyltransferase (DNMT) inhibitors in colorectal, breast, and ovarian cancer cells." (PMID 39057134, 2024). "In ovarian carcinoma, collagen can stabilize and activate DNA methyltransferase 1 (DNMT1), which leads to methylation and downregulation of miR-509-3p promoter, an anti-tumor miRNA that also suppresses chemoresistance." (PMID 39769286, 2024). "Herein, R54 reduced Foxp3 and DNMT1 transcription, as previously reported in murine ovarian cancer, where the CXCR4 inhibitor, AMD3100, selectively reduced intratumoral Foxp3 Tregs and DNMT1 determining loss of Tregs suppressive function in vitro and in vivo." (PMID 38704478, 2024). "F-LP/gDNMT1 effectively mutated endogenous DNMT1 in vitro and then expressed Cas9 endonuclease and downregulated DNMT1 in vivo in paclitaxel-sensitive and resistant ovarian cancers." (PMID 39125873, 2024). "Previous studies in ovarian cancer also found an increase in E-cadherin protein with DNMT1-targeting therapy, corresponding to a decrease in methylation levels observed at the E-cadherin gene promoter." (PMID 37345101, 2023). "Liposome/CRISPR plasmid complex has been used to downregulate DNA methyltransferase 1 (DNMT1) in ovarian cancer." (PMID 37679807, 2023). "On the other hand, ovarian cancer tumorsphere formation was also reflected by decreased expression of DNMT1." (PMID 37189618, 2023). "Overexpression of miR-152 upregulated cisplatin sensitivity both in vitro and in vivo by suppressing DNMT1 directly in ovarian cancer cells." (PMID 36959680, 2023). "There results indicate that COL11A1 downregulates miR-509-3p expression in ovarian cancer cells by inhibiting the binding of DNMT1 to the miR-509-3p promoter." (PMID 37386587, 2023). "In ovarian cancer, Han and colleagues have reported an interesting feedback loop between miR-30a/c-5p and DNMT1." (PMID 37239435, 2023). "TGF-β induced both expression and activity of DNA methyltransferases (DNMT) -1, -3A, and -3B in ovarian cancer cells, while in vitro phosphorylation of DNMT1 by PKCζ reduced its methyltransferase activity." (PMID 35215560, 2022). "Another DNMT1 inhibitor guadecitabine was tested in combination with carboplatin in platinum-resistant recurrent ovarian cancer, in a II phase multicenter randomized clinical trial." (PMID 35269636, 2022). "Exosomal DNA methyltransferase 1 (DNMT1) transcripts were highly expressed in exosomes derived from ovarian cancer cells and enhanced the cisplatin resistance of ovarian cancer cells." (PMID 35024437, 2022). "Further, a study also suggested that EVs released from ovarian cancer cells induce cisplatin resistance because they contained DNA methyltransferase 1 (DNMT1)." (PMID 35814435, 2022). "DNA methyltransferase 1 (DNMT1) mRNA was found to play a key role in EV-mediated cisplatin resistance in an ovarian cancer xenograft mouse model." (PMID 35159299, 2022). "In research published in 2015, DNMT1 mRNA expression was described to be strongly related to decitabine sensitivity in ovarian cancer cells, which was mediated by the RAS/MEK/DNMT1 pathway." (PMID 35838271, 2022). "In epithelial ovarian cancer, miR-152 functioned through suppressing DNA methyltransferase 1 (DNMT1) to inhibit ovarian cancer cell proliferation and promote apoptosis." (PMID 34680020, 2021). "The combination of EZH2 and DNMT1 inhibitors in ovarian cancer also promoted the intratumoral expression of TH1 chemokines (CXCL9 and CXCL10) expression, which correlated with improved efficacy of adoptive T cell transfer and checkpoint inhibition." (PMID 33859645, 2021). "In ovarian cancer, DNA methyltransferase 1 (DNMT1), which is responsible for DNA methylation, also regulated the expression of these chemokines." (PMID 32121394, 2020).
ovarian carcinoma (continued). "For example, ROS inhibit the expression of miR-199a and miR-125b in ovarian cancer cells via increasing promoter methylation of the miR-199a and miR-125b genes, which is mediated by the DNA methyltransferase 1 (DNMT1)." (PMID 31717786, 2019). "As reported that the high expression of DNMT1 supported the potential contribution of ovarian cancer stem cells to platinum resistance, we performed drug sensitivity assays by CCK8 with cisplatin (DDP) which are commonly used of chemotherapy for ESCC." (PMID 29721170, 2018). "Our findings suggest that STON2 depression up-regulates MUC1 expression, along with inhibition of DNMT1, in a process that contributes to the maintenance of stem-like properties in ovarian cancer cells." (PMID 30518424, 2018). "Pyrosequencing data also revealed that the methylation level was reduced in the MUC1 promoter region in STON2 or DNMT1 knocked down ovarian cancer cells." (PMID 30518424, 2018). "Our findings reveal a novel mechanism by which UBC13 regulates paclitaxel sensitivity through a DNMT1-CHFR-Aurora A pathway in ovarian cancer cells." (PMID 29367628, 2018). "Our results suggest that HDAC1 and DNMT1 contribute to the suppression of RGS10 during acquired chemoresistance and support growing evidence that inhibition of HDAC1/DNMT1 represent novel therapeutic approaches to overcoming ovarian cancer chemoresistance." (PMID 24475290, 2014). "Together these data indicate that accumulation of DNMT1 at the RGS10 promoter likely contributes to suppression of RGS10 during ovarian cancer chemoresistance." (PMID 24475290, 2014). "We identify two important epigenetic regulators, HDAC1 and DNMT1, that exhibit aberrant association with RGS10 promoters in chemoresistant ovarian cancer cells." (PMID 24475290, 2014). "We identify two important epigenetic regulators, HDAC1 and DNMT1, which are highly associated with the RGS10 promoter in chemoresistant ovarian cancer cells." (PMID 24475290, 2014). "Our results suggest that HDAC1 and DNMT1 contribute to the suppression of RGS10 during acquired chemoresistance and support inhibition of HDAC1 and DNMT1 as an adjuvant therapeutic approach to overcome ovarian cancer chemoresistance." (PMID 24475290, 2014). "In contrast to total protein abundance, ChIP assays reveal that binding of DNMT1 is significantly increased at the RGS10 promoter in chemoresistant cells as compared to chemosensitive ovarian cancer cells." (PMID 24475290, 2014). "The lowest p values of the trend test were observed for the DNMT1 rs2228611 and rs759920 SNPs in patients with ovarian cancer (ptrend = 0.0118 and ptrend = 0.0173, respectively)." (PMID 23666104, 2013). "In summary, our studies demonstrate that the mRNA expression of DNMT1, DNMT3b and class I HDACs was increased in ovarian cancers." (PMID 23420051, 2013). "The overall high rate of expression for class I HDACs, DNMT1 and DNMT3b suggested that these mRNAs should be explored as predictive factors in ovarian cancer." (PMID 23420051, 2013). "The data showed that expression of DNMT1, DNMT3a, and DNMT3b was observed in 76 (53.5%), 92 (64.8%) and 79 (55.6%) of 142 cases of ovarian cancer tissues, respectively." (PMID 22768205, 2012). "Another report demonstrated that expression of DNMT1 mRNA levels in ovarian cancer HeyA8 and HeyC2 cell lines was higher than that of normal ovarian epithelial cells." (PMID 22768205, 2012). "During EOC disease progression, DNMT1 expression is elevated, is correlated with increased DNA and histone methylation with advanced, chemoresistant ovarian cancer." (PMID 19025622, 2008). "F‐LP formed stable lipoplexes with the DNA methyltransferase 1 (DNMT1) gene (gDNMT1), namely, F‐LP/gDNMT1, which resulted in successful tumor growth inhibition of both paclitaxel‐sensitive and paclitaxel‐resistant ovarian cancers as well as downregulated DNMT1 in vivo." (PMID 37166046, 2023).
ovarian carcinoma (continued). "The II phase clinical trial on DNMT1 inhibitor decitabine combined with platinum-based chemotherapy was performed in the group of 29 patients with recurrent partially chemo-sensitive (relapse 6–12 months after first line chemotherapy) ovarian cancer." (PMID 35269636, 2022). "It was reported that overexpressing miR-152 could suppress proliferation and promote apoptosis through targeting of DNMT1 in ovarian cancer cells." (PMID 33269380, 2021). "Furthermore, another bidirectional regulation has been described between DNA methyltransferases and miRNAs, with importance in ovarian cancer: a feedback loop between miR-30a/c-5p and DNMT1 that mediates cisplatin resistance." (PMID 34298969, 2021). "Another study has shown that S-allylcysteine derived from garlic could inhibit the expression of DNA methyltransferase 1 and then induce global DNA hypomethylation in human ovarian cancer cells." (PMID 33992091, 2021). "The identified protein network revealed that STON2 modulate stemness in ovarian cancer cells via epigenetic effectors such as DNMT1, and therefore, STON2 has a role in ovarian cancer biology and could represent a therapeutic target." (PMID 31781477, 2019). "Given that ZC3H18 depletion caused BRCA1 promoter methylation and E2F1 recruitment to the BRCA1 promoter, we reasoned that E2F1 might repress BRCA1 expression in ovarian cancer cells by recruiting DNMT1 when ZC3H18 was depleted." (PMID 31604914, 2019). "Furthermore, silencing DNA methyltransferase 1 (DNMT1) or 3B (DNMT3B) restored ALDH1A2 expression in ovarian cancer cell lines." (PMID 31615043, 2019). "Exosomal DNMT1 enhances the resistance to cisplatin in ovarian cancer cells." (PMID 31615043, 2019). "Interestingly, ovarian cancer progression is also accompanied by increased expression of enzymes responsible for DNA methylation, DNMT1 and DNMT3a, and expression levels correlate well with a poor prognosis of patients with ovarian cancer." (PMID 31426393, 2019). "Our results suggest that DNMT1 regulates CHFR expression by altering its promoter DNA methylation in ovarian cancer cells, but such a regulating effect may be variable among different cancers." (PMID 29367628, 2018). "Furthermore, we found that the DNMT1 protein half-life in the paclitaxel-resistant ovarian cancer cells was increased compared to the sensitive parental cells." (PMID 29367628, 2018). "Moreover, miR-152 is significantly reduced in ovarian cancer cells, and miR-152 regulates ovarian cancer cisplatin resistance by targeting DNMT1." (PMID 28056089, 2017). "Regarding the significance of the demethylating effect of hydralazine in the induction of apoptosis, a reduction of DNMT1 protein level and activity has been observed in ovarian cancer cells in response to treatment for one day with hydralazine in a range of doses from 150 to 600 μM." (PMID 26942461, 2016). "In addition, miR-152 and miR-185 were shown to be involved in cisplatin-resistant ovarian cancer in vitro and in vivo through their direct targeting of DNMT1." (PMID 24987964, 2014). "Additionally, the results of immunohistochemical staining demonstrated that DNMT1 and DNMT3b were significantly increased in ovarian cancer samples." (PMID 23420051, 2013). "Similarly, the relative expressions of DNMT1 and DNMT3b mRNA in ovarian cancers (n=22) were significantly higher than those in normal tissues (n=8), particularly for DNMT1 (P<0.01)." (PMID 23420051, 2013). "In this study, we collected 142 cases of epithelial ovarian carcinoma samples and 44 cases of benign ovarian tumors for detection of DNMT1, DNMT3a, and DNMT3b protein expressions in order to determine the role of DNMT proteins in ovarian cancer and clinical significance." (PMID 22768205, 2012). "However, DNMT1 rs2228611 did not present a significant association with ovarian cancer development in either dominant or recessive inheritance models." (PMID 39597087, 2024).
ovarian carcinoma (continued). "The miR-509-3p/DNMT1/SUMO-3 axis may be an ovarian cancer treatment target." (PMID 37386587, 2023). "We hypothesized that up-regulation of miR-148a and miR-152 by treatment with 5-Aza and TSA could reverse cisplatin resistance through DNMT1 suppression in ovarian cancer and miR-148a and miR-152 down-regulation might be due to DNA methylation and histone de-acetylation." (PMID 33680048, 2020). "A recent study using mouse models of ovarian cancer has shown that the reduced production of CXCL9 and CXCL10 from cancer cells is caused by enhancer of zeste homolog 2 (EZH2) mediated histone modification and DNA methyltransferase 1 (DNMT1) mediated DNA methylation of the chemokine genes." (PMID 30483271, 2018). "MiR-152 and miR-185 could co- target DNMT1 (DNA Methyltransferase 1) in ovarian cancer cells." (PMID 29323178, 2018). "Furthermore, we aimed to study whether these DNMT1, DNMT3A and DNMT3B SNPs can be a genetic risk factor of ovarian cancer." (PMID 23666104, 2013). "Exosomes from ovarian cancer patients and SKOV3 ovarian cancer cell line highly enriched with DNMT-1 protein levels abrogated the cytotoxic activity of cisplatin and enhanced tumor growth in vivo." (PMID 38796525, 2024). "More recently, the expressions of DNMT1, DNMT3A and DNMT3B were examined by immunohistochemistry in ovarian cancers and benign tumors." (PMID 37894317, 2023). "By contrast, the overexpression of DNMT1 promotes cisplatin resistance and partial EMT in ovarian cancer cells." (PMID 37239435, 2023). "We next analysed the relationship between CHD4 and methylation enzymes (DNMT1, DNMT3B, EZH2, and G9a) in ovarian cancer." (PMID 36681835, 2023). "Due to the accumulation of DNA methyltransferase 1 (DNMT1) and class I Histone deacetylases (HDACs) at the RGS2 promoter region, the expression of RGS2 gene is inhibited in ovarian cancer cells." (PMID 37649067, 2023). "miR-152 inhibited the proliferation, migration, or invasion by targeting the DNMT1 3′UTR directly in hepatitis B virus-related hepatocellular carcinoma, ovarian cancer, glioma, nasopharyngeal cancer and bladder cancer cells." (PMID 36959680, 2023). "RGS10 expression is regulated by DNMT1 and HDAC1, and dysregulation of RGS10 reduces chemoresistance in ovarian cancer cells." (PMID 37649067, 2023). "While the expression of NOG, S1PR1, BTG4, and CREB5 genes was significantly increased, that of RASSF9, DNMT1, BST2, and SETD1A genes was significantly decreased in CFP1-deleted A2780 and ES-2 ovarian cancer cells, based on qRT-PCR results." (PMID 35864225, 2022). "Similar results were obtained in another model of ovarian cancer, in which the phospholipase inhibitor GW4869 was shown to inhibit the exosomal DNA methyltransferase 1 (DNMT1)-mediated cisplatin resistance in cells, and to increase apoptosis." (PMID 36591453, 2022). "In recent studies, it was demonstrated that zebularine and 5-aza-dC down-regulate DNMT-1, DNMT-3a, and DNMT-3b in ovarian cancer cell lines." (PMID 34903991, 2021). "In contrast, our studies in multiple ovarian cancer cell lines found that E2F1 represses BRCA1 expression, and that this repression requires the DNA methyltransferase DNMT1 and is correlated with CpG hypermethylation of the BRCA1 promoter." (PMID 31604914, 2019). "The mRNA levels of DNMT1, DNMT3A, and DNMT3B were strongly elevated in ovarian cancer tissues compared to those in normal ovarian tissues, according to Oncomine." (PMID 31615043, 2019). "Consistent with the data of these reports, we observed that the mRNA levels of DNMT1, DNMT3A, and DNMT3B were elevated in ovarian cancer tissues compared to those in normal epithelial ovarian cells." (PMID 31615043, 2019). "For example, in ovarian cancer, tumor cell production of chemokines CXCL9 and CXCL10 are epigenetically repressed by EZH2-mediated H3K27me3 and DNMT1-mediated DNA methylation." (PMID 30740111, 2018).
ovarian carcinoma (continued). "STON2 knockdown promotes stem-like properties in ovarian cancer cells and its overexpression suppresses MUC1-induced sphere formation in OCSCs, in which DNMT1-mediated methylation in the promoter region of MUC1 has been confirmed to be modulated by STON2." (PMID 30518424, 2018). "Our findings together suggest that UBC13 controls DNMT1 stability via ubiquitination and DNMT1, probably through CHFR and Aurora A, participates in UBC13 regulation of the sensitivity of ovarian cancer cells to paclitaxel." (PMID 29367628, 2018). "TGFβ has been shown to elevate CD133 expression via demethylation of the CD133 P1 promoter by inhibiting the expression of DNMT1 and DNMT3β and Promoter methylation decreased CD133 expression in ovarian cancer and glioblastoma." (PMID 25301737, 2014). "Our results further imply that the increased expression of DNMT1 and HDAC1 results in the generation of repressive complexes which target RGS10 promoters and cooperate in regulating ovarian cancer progression." (PMID 24475290, 2014). "In this manner, DNMT1 and HDAC1 synergistically contribute suppression of RGS10 transcription expression as ovarian cancer progresses." (PMID 24475290, 2014). "In our current study, we demonstrate specific contribution of two important epigenetic regulators, HDAC1 and DNMT1, to the suppression of RGS10 expression in chemoresistant ovarian cancer cells." (PMID 24475290, 2014). "The mRNA expression of DNMT1, DNMT3b, HDAC1 and HDAC2 were particularly prominent in high-grade tumors in ovarian cancers, which indicated that they may be the biomarkers of tumor aggressiveness and proliferation, as their high expression is closely associated with ovarian carcinoma progression." (PMID 23420051, 2013). "PARP1 can enhance DNA methyltransferase 1 (DNMT1) expression by maintaining the unmethylated state of the DNMT1 promoter, so it can be predicted that up-regulation expression of DNMT1 may be beneficial in resisting genome-wide demethylation during the progression of ovarian cancer." (PMID 23442605, 2013). "In addition, we also found that expression of DNMT1 was higher in the unilateral ovarian cancer than in bilateral ovarian cancer, which may indicate the difference of the unilateral and bilateral ovarian cancer in terms of the biological characteristics, genetics, and mechanism." (PMID 22768205, 2012). "In ovarian cancer cell line CP70, DNMT1 siRNA treatment led to a partial removal of DNA methylation from three inactive promoter CpG islands, TWIST, RASSF1A, and HIN-1, and restored the expression of these genes." (PMID 21999220, 2011). "In ovarian cancer cells, SFN inhibits degradation of retinoblastoma protein (Rb), which directly binds to DNMT1, sequesters its activity and disrupts formation of DNMT-DNA complexes." (PMID 22303414, 2011). "For instance, trimethylation at H3K27 represses the production of CXCL9 and CXCL10 in ovarian cancer, establishing an immune-suppressive TME, while DNMT1 is responsible for the decreased CXCL12 in osteosarcomas, resulting in reduced CTL recruitment at the cancer site." (PMID 39000359, 2024). "Annexin A3, P-glycoprotein (P-gp), signal transducer and activator of transcription 3 (STAT3), FAS, DNA methyltransferase-I (DNMT-1), multidrug resistance protein 2 (MRP2), ATP 7A, and ATP 7B are exosomal proteins that promote drug resistance in ovarian cancer cells." (PMID 38796525, 2024). "TGFβ stimulation in ovarian cancer cells treated with non-specific DNMT inhibitor SGI-110 or guadecitabine led to increased activity and nuclear localization of particularly DNMT1 and prevention of CDH1 silencing, which suggests a TGFβ-DNMT1-CDH1 pathway." (PMID 37566041, 2023).